ADAM17 (ADAM metallopeptidase domain 17)
Diseases named in the same sentence as ADAM17 in open-access papers (continued):
Sharing a sentence is not in itself a finding about the gene and the disease.
myeloma (4 papers, 2012 to 2026). "Furthermore, the mechanism responsible for generating sRANKL is unknown, but may include proteolytic cleavage of a membrane-bound RANKL isoform, as myeloma cells can shed membrane bound molecules and express ADAM17, a proteinase capable of shedding RANKL." (PMID 22952578, 2012). "Upon stimulation, we observed an increase of ADAM17 in HT1080 cells, and no significant change in the Hodgkin’s lymphoma cell line L248, HeLa cells, U266B1 myeloma cells, Panc89 or Jurkat variants." (PMID 24130797, 2013).
oral squamous cell carcinoma (4 papers, 2014 to 2023). "Furthermore, miR-224 can inhibit the growth and invasion of oral squamous cell carcinoma (OSCC) cells by targeting ADAM17 expression." (PMID 37760235, 2023). "Despite the known crosstalk between ADAM17 and EGFR, which has been considered a promising targeted therapy in oral squamous cell carcinoma (OSCC), the role of ADAM17 in OSCC development is not clear." (PMID 24495306, 2014).
osteoarthritis (4 papers, 2014 to 2022). A noninflammatory degenerative joint disease occurring chiefly in older persons, characterized by degeneration of the articular cartilage, hypertrophy of bone at the margins and changes in the synovial membrane. "ADAM-17 expression was measured by enzyme-linked immunosorbent assays (ELISAs) in serum from normal (NL) subjects, osteoarthritis (OA) patients, and RA patients." (PMID 30071898, 2018).
pancreatitis (4 papers, 2019 to 2025). Inflammation of the pancreas. "In addition, genes targeting ADAM17 (Adam17ex/ex mice) and treatments (ADAM17 predomain inhibitors [A17pro]) improved experimental pancreatitis, which was associated with a reduction in the IL-6 transsignaling/STAT3 axis." (PMID 36969002, 2023). "Studies on the metalloprotease ADAM17 in caerulein-induced pancreatitis showed that an inhibition of ADAM17 reduces IL-6 trans-signaling and leukocyte recruitment into damaged pancreatic tissue." (PMID 40560328, 2025). "Clinically, the ADAM17/IL-6/STAT3 pathway is elevated in pancreatitis patients, linking ADAM17 to both inflammation and potential PDAC development." (PMID 40427200, 2025). "It has previously been shown that ADAM17 mRNA is upregulated in the pancreas from patients with pancreatitis and in PBMCs and liver tissue from patients with chronically inflamed hepatic iron-overload compared to patients without iron-overload." (PMID 31507587, 2019). "Taken together, our findings suggest that ADAM17 protease plays a key role in the pathogenesis of pancreatitis, which may provide ideas for designing new treatment options to combat pancreatitis." (PMID 36969002, 2023). "In addition, upregulation of the ADAM17/IL-6 transsignal/STAT3 axis is a feature in patients with pancreatitis." (PMID 36969002, 2023). "ADAM17 expression upregulated in pancreatic tissues in animal models of pancreatitis." (PMID 36969002, 2023).
renal cell carcinoma (4 papers, 2016 to 2022). "For instance, functional inhibition of ADAM17 leads to decreased migration and proliferation in renal cell cancer." (PMID 29662625, 2018). "This hypothesis is strengthened by a study describing a reciprocal negative feedback loop between miR-145 and ADAM17 expression in renal cell carcinoma, in which miR-145 negatively regulates ADAM17 and ADAM17, in turn, negatively regulates miR-145 expression." (PMID 36293469, 2022). "Another study examining the relationship between ADAM17 and Notch signaling showed that ADAM17 is a key enzyme for activation of the Notch signaling pathway, and that inhibition of its activity effectively promotes apoptosis and impairs invasion ability in renal cell carcinoma." (PMID 26993601, 2016).
squamous cell carcinoma (4 papers, 2014 to 2019). A carcinoma arising from squamous epithelial cells. "In addition, the tumor size, tumor proliferative activity, tumor collagenase activity and MS-based proteomics of tumor tissues have been evaluated by injecting tumorigenic squamous carcinoma cells (SCC-9) overexpressing ADAM17 in immunodeficient mice." (PMID 24495306, 2014).
triple-negative breast carcinoma (4 papers, 2022 to 2025). An invasive breast carcinoma which is negative for expression of estrogen receptor (ER), progesterone receptor (PR), and human epidermal growth factor receptor 2 (HER2). "To further evaluate the correlation between ADAM17 and the protumorigenic macrophage markers, we stained a triple-negative breast cancer cohort, including tumor tissue from 159 patients, for ADAM17 by immunohistochemistry (IHC)." (PMID 35998057, 2022). "D8P1C1, an anti-ADAM17 monoclonal antibody, remarkably inhibited tumor growth in triple-negative breast cancer mouse models." (PMID 36466812, 2022). "In 35.6% of the samples, we detected a strong staining of ADAM17 in the tumor, confirming previous reports of high ADAM17 expression in triple-negative breast cancer." (PMID 35998057, 2022). "By using bioinformatics analysis based on the TCGA dataset and immunohistochemical analysis from triple-negative breast cancer cohort, the authors first confirmed that highly expressed ADAM17 in tumors is positively correlated with tumorigenic macrophage markers CD163 or CD206." (PMID 36466812, 2022). "Ectoproteases may also aid in identifying and developing novel strategies for cancer treatment, including the difficult-to-treat triple-negative breast cancer through the inhibition of ADAM17 or MMP9." (PMID 35158891, 2022). "In triple-negative breast cancer (TNBC), ADAM17 promotes malignancy by driving proliferation, invasion, and angiogenesis through the activation of the EGFR-PI3K-AKT signalling pathway." (PMID 40427200, 2025). "ADAM17 can mediate the release of sTNFR1 and sTNFR2, which inhibit the secretion of metastasis-promoting chemokines (CXCL8, CCL5, CXCL) and induce anti-metastasis effects in triple-negative breast cancer cells." (PMID 36466812, 2022).
acute kidney injury (3 papers, 2020 to 2021). Sudden and sustained deterioration of the kidney function characterized by decreased glomerular filtration rate, increased serum creatinine or oliguria. "The expression of apparatus mediating SARS-CoV-2 entry, including angiotensin-converting enzyme 2, transmembrane protease serine 2 (TMPRSS2) and a disintegrin and metalloprotease 17 (ADAM17), within the renal tubular cells is highly associated with acute kidney injury mediated by SARS-CoV-2." (PMID 33153216, 2020). "The downregulation of renal ADAM17 in rats with CHF, may explain the relatively limited incidence of acute kidney injury (AKI) in COVID‐19 disease, as opposed to the substantial pulmonary and myocardial injuries." (PMID 33660945, 2021).
allergic asthma (3 papers, 2007 to 2022). A asthma with a basis in a pathological type I hypersensitivity reaction. "Thus, IL-13-induced, ADAM17-mediated release of TGFα, and subsequent epithelial cell proliferation, could contribute to the epithelial hypertrophy, as well as other features, associated with airway remodeling in allergic asthma." (PMID 17620132, 2007). "In allergic asthma, downregulation of ACE2 has been associated with a type 2 immune profile, through which increased levels of IL-13 might reduce the expression of disintegrin and metalloprotease 17 (ADAM-17)." (PMID 35920529, 2022).
aortic aneurysm (3 papers, 2023 to 2026). A ruptured aneurysm located in the wall of the proximal portion of the descending aorta proceeding from the arch of the aorta. "In the chronic pathological processes such as aortic aneurysm formation and ventricular remodeling, the Angiotensin II (Ang II)-ADAM17-EGFR signaling pathway plays a significant role." (PMID 41050403, 2025). "In contrast, the most studied member, ADAM17, has been found to play critical roles in aortic aneurysm development in both mice and humans." (PMID 37079380, 2023). "Third, in mice, IH was demonstrated to increase vascular cell production of matrix metalloproteinases (MMPs) and metalloproteinases, including ADAM‐17 and the elastases MMP2 and MMP9, resulting in alteration of elastin in the aortic wall and the development of aortic aneurysms." (PMID 41541542, 2026).
astrocytoma (3 papers, 2016 to 2022). "We found that P2Y11 promoted the release (shedding) of soluble TNF receptors through TNF-α converting enzyme (TACE), also known as ADAM17 (a disintegrin and metalloprotease 17), both in astrocytoma cells (sTNFR1) and in human M2 macrophages (sTNFR2)." (PMID 36107259, 2022). "Carnosic acid treatment is reported to enhance the messenger RNA (mRNA) expression of ADAM17 in human astrocytoma cells, and IL-1α stimulates ADAM17 synthesis in human primary astrocytes." (PMID 27549131, 2016). "Similarly, in U373MG astrocytoma cells CA inhibited amyloid β peptide production and release and this was associated, at least partially, with activation of the α-secretase TACE/ADAM17." (PMID 27869665, 2016).
autism (3 papers, 2013 to 2023). Persistent deficits in social interaction and communication and interaction as well as a markedly restricted repertoire of activity and interest as well as repetitive patterns of behavior. "One of the purported α-secretase enzymes that cleaves βAPP and generates sAPPα, A Disintegrin and Metalloproteinase Domain 17 (ADAM17) also known as tumor necrosis factor-α converting enzyme (TACE), increases in autism brain tissue." (PMID 31024350, 2019). "It is not yet clear if the abnormal level of TNF-α is due to pro-inflammatory conditions or to disturbed associated signaling that takes place throughout the pathogenesis of autism, such as the reported down regulation of ADAM17, which is as a TNF converting enzyme." (PMID 37371450, 2023). "Furthermore, linkage was found between a region of human chromosome 2 that contains the ADAM17 gene and autism." (PMID 23801940, 2013). "In the case of APP, loss of function would favor the amyloidogenic pathway leading to AD while gain of function toxicity would favor the non-amyloidogenic pathway leading to excessive ADAM17, sAPPα, and brain overgrowth associated with autism." (PMID 23801940, 2013). "While ADAM17 itself has not been specifically studied in association with autism, the cerebrospinal fluid to serum ratio for TNF-α is elevated in subjects with autism compared to other pathological states." (PMID 23801940, 2013).
bladder cancer (3 papers, 2021 to 2025). "To better understand the immunologic mechanisms underlying BCG failure, we have examined for the first time the expression of ADAM17, a disintegrin and metalloproteinase (ADAM) family member in BCG-nonresponsive bladder cancer." (PMID 33672843, 2021).
cholangiocarcinoma (3 papers, 2015 to 2022). A carcinoma that arises from the intrahepatic biliary tree (intrahepatic cholangiocarcinoma) or from the junction, or adjacent to the junction, of the right and left hepatic ducts (hilar cholangiocarcinoma). "LPS has recently been shown to functionally transactivate cholangiocarcinoma cell EGFR through ADAM17 (TACE)-dependent release of TGFα." (PMID 25915403, 2015).
cholestasis (3 papers, 2013 to 2021). Impairment of the bile flow caused by obstruction within the liver, or outside the liver in the bile duct system. "In our current study, we now show that inhibition of ADAM17 ameliorates cholestasis-associated sickness behavior development, as reflected by an increase in time spent engaging in social interaction and a decrease in time spent remaining immobile in DPC 333-treated cholestatic mice." (PMID 35095853, 2021). "Our group has previously defined critical roles for the ADAM17-regulated cytokines TNFα and IL-6, cytokine receptor TNFRI, and immune cell adhesion molecule VCAM-1, in cholestasis associated sickness behavior development in BDL mice." (PMID 35095853, 2021). "Therefore, we evaluated the hepatic expression/activity of ADAM17, and the impact of ADAM17 inhibition, on liver injury and sickness behavior development in a well characterized murine model of cholestasis." (PMID 35095853, 2021). "The use of TMI-005 could be considered in future studies to broaden the generalizability of our findings of ADAM17 inhibition in cholestasis." (PMID 35095853, 2021). "We hypothesized that UDCA modulates ADAM17 activity, resulting in amelioration of cholestasis in a murine model of bile duct ligation (BDL)." (PMID 24172289, 2013). "Further studies are required to better characterize the role of ADAM17 within the liver microenvironment and inflammatory milieu as it pertains to cholangiocyte response, bile duct injury, TGFα, EGFR signaling and overall cholestasis." (PMID 35095853, 2021). "Interestingly, we also observed ADAM17 expressing immune cells infiltrating bile duct epithelium in both PBC and PSC patients, a process that may further alter cholangiocyte function, signaling, and responses to cholestasis." (PMID 35095853, 2021).
colorectal tumor (3 papers, 2019 to 2023). "Although ADAM17 has been shown to be required for colorectal tumour growth, the possible contribution of iRhom2 phosphorylation in colorectal tumorigenesis is currently unexplored." (PMID 35971826, 2022). "While it was demonstrated that colorectal tumor formation requires cleavage of IL-6R by ADAM17 to mediate soluble (s)IL-6R-dependent IL-6 trans-signaling, it further underlines the significance of ADAM17 in CRC pathology." (PMID 31060243, 2019). "As ADAM17-mediated promotion of angiogenesis was reported to involve sMCAM release, we aimed to unravel how ADAM17 inhibition could also affect MC38 mouse colorectal tumor angiogenesis and lymphangiogenesis." (PMID 38137406, 2023).
cystic fibrosis (3 papers, 2018 to 2021). Autosomal recessive disorder caused by pathogenic variants in the CFTR gene (cystic fibrosis transmembrane conductance regulator), which encodes a chloride and bicarbonate channel expressed in epithelial cells, and follow the diagnosis criteria. "Consequently, a disturbance in the control of the complex EGFR/ADAM17/STAT3 pathway would likely play a role in Cystic Fibrosis and COPD chronic lung disease." (PMID 29540993, 2018).
dermatitis (3 papers, 2015 to 2018). An inflammatory process affecting the skin. "A previous study showed that sustained deficiency of ADAM17 in the epidermis of wild‐type mice results in epidermal barrier defects, and subsequently dermatitis and myeloproliferative disease; that is, a significant increase in the myeloid‐cell infiltration." (PMID 29632822, 2018). "Thus, to determine whether ADAM17 deficiency also causes dermatitis in Rhbdf2cub/cub mice, we examined the skin phenotype of Rhbdf2cub/cubADAM17flox/floxK14‐Cre mice in comparison with that of ADAM17flox/floxK14‐Cre and ADAM17flox/flox control mice." (PMID 29632822, 2018). "The mutant mice with epidermal deletion [by K5 (or K14)-Cre-mediated deletion of a floxed gene] of JunB (transcription factor), a disintegrin and metalloproteinase 17 (ADAM17) or Notch receptors/their signal transducers exhibited both AD-like skin inflammation and MPN." (PMID 26379670, 2015). "• Dermatitis and myeloproliferative disease in Rhbdf2cub/cub mice lacking ADAM17 specifically in the skin." (PMID 30022999, 2018).
diabetic retinopathy (3 papers, 2020 to 2024). "In diabetic retinopathy, the ADAM17-mediated cleavage of CX3CL1 and VCAM-1 in retinal endothelial cells has been associated with vascular leakage and retinal neovascularization." (PMID 37762417, 2023). "ADAM17 activity was shown to contribute to a number of vascular pathologies, but its role in the context of diabetic retinopathy (DR) is not determined." (PMID 32024241, 2020).
endotoxemia (3 papers, 2009 to 2017). "Inhibition of ADAM17 as well as global or myeloid cell-restricted deletion of ADAM17 in mice results in reduced systemic TNF-α levels following LPS treatment and protects mice from fatal endotoxemia." (PMID 28877252, 2017).
esophageal cancer (3 papers, 2015 to 2022). A primary or metastatic malignant neoplasm involving the esophagus. "ADAM17 and esophageal cancer studies were rarely reported, Sakamoto, etc. used the RT-PCR and western blot analysis protein electrophoresis methods, they detected the elevated ADAMTS16 protein expression in esophageal tissues." (PMID 25351873, 2015). "This indicates that ADAM17 and EGFR expression may increase the risk of esophageal cancer mortality." (PMID 25351873, 2015). "However, there are limited studies reporting the expression of ADAM17 in esophageal cancer." (PMID 25351873, 2015). "An improved understanding of the importance of ADAM17 and the downstream EGFR signaling pathway in esophageal cancer invasion may aid in the development of therapeutic strategies aimed at reducing the invasiveness of esophageal cancer." (PMID 25351873, 2015).
Hepatic steatosis (3 papers, 2011 to 2024). Steatosis is a term used to denote lipid accumulation within hepatocytes. "This evidence was accompanied by a lower cholesterol level in liver extract, indicating that only hepatocyte specific deletion of ADAM17 has the protective effects on liver steatosis." (PMID 28751722, 2017). "The association of TIMP3 with liver steatosis is explained, but only in part by gut microbiome dysbiosis, suggesting that TIMP3/ADAM17 dyad exerts both broad and local effects to modulate immune and metabolic pathways." (PMID 28751722, 2017).
hilar cholangiocarcinoma (3 papers, 2018 to 2022). A cholangiocarcinoma that arises from the junction, or adjacent to the junction, of the right and left hepatic ducts. "Specific a-disintegrin and metalloproteinase (ADAM) are overexpressed in many human cancers and related with poor clinical outcomes and tumor progression, silencing FoxM1 led to an inhibition of cell proliferation, tumor growth induced by ADAM-17 in hilar cholangiocarcinoma." (PMID 30580327, 2018).
intestinal tumors (3 papers, 2017 to 2019). "Immunohistochemistry showed that DCA treatment increased the percentage of positive cells of ADAM‐17 in intestinal tumour in Apcmin/+ mice (75.00 ± 2.35 vs 36.33 ± 1.94, P < .001)." (PMID 29956475, 2018). "We then investigated the effects of DCA on ADAM‐17/EGFR signalling axis in intestinal tumour development." (PMID 29956475, 2018). "Apart from maintaining normal intestinal homeostasis, ADAM17 and ErbB signaling is of great importance for intestinal epithelial regeneration, and in the development of intestinal tumors." (PMID 29312533, 2017). "Strikingly, in the absence of ADAM17 activity, almost no intestinal tumors were detected and the few remaining tumors were only of low-grade dysplasia whereas in the presence of ADAM17, also high-grade dysplasias and invasive carcinomas were detected." (PMID 31694340, 2019). "ADAM‐17/EGFR signalling axis was also activated in intestinal tumours of DCA‐treated Apcmin/+ mice, whereas no significant change occurred in tumour adjacent tissues after DCA exposure." (PMID 29956475, 2018).
ischemic heart disease (3 papers, 2022 to 2023). "It should be emphasized that ADAM17 has a documented role in the formation of the inflammatory process and, consequently, in diseases that are caused by chronic inflammation, such as DMT2, ischemic heart disease or CRC." (PMID 36286024, 2022).
kidney damage (3 papers, 2013 to 2021). "Based on these data, we postulate that during early stages of kidney damage, renal ACE2 and sheddase activity of ADAM17 increase in the event of high circulating Ang II, while expression of renal TIMP3 is reduced." (PMID 23646149, 2013). "ADAM17 and its inhibitor TIMP3 are involved in nephropathy, but their role in diabetic kidney disease (DKD) is unclear." (PMID 23401241, 2013).